ZNF280D (zinc finger protein 280D)
Description:
May function as a transcription factor.
Synonyms: SUHW4; ZNF634; FLJ20086
Tractability: PROTAC: UniProt records ubiquitination sites on it; ubiquitination databases record sites on it.
Target class: Transcription factor
Gene: Protein-coding gene on chromosome 15 (56,630,176 to 56,734,086, reverse strand). Ensembl gene ENSG00000137871.
Subcellular location: Nucleus
Subcellular location (Human Protein Atlas): Cytosol; Nucleoplasm; Centrosome; Golgi apparatus
Gene Ontology:
Molecular function: DNA-binding transcription factor activity, RNA polymerase II-specific; RNA polymerase II cis-regulatory region sequence-specific DNA binding
Biological process: regulation of DNA-templated transcription; regulation of transcription by RNA polymerase II
Cellular component: nucleus
Genetic constraint (gnomAD): Loss-of-function variants: 22 observed, 62.95 expected, observed/expected ratio (o/e) 0.35, 90% interval 0.25 to 0.5. The upper end of that interval is the gene's LOEUF score, 0.5, which puts it in group 2 of 6, group 1 being the genes least tolerant of losing a copy. Missense variants: 853 observed, 942.46 expected, observed/expected ratio (o/e) 0.91, 90% interval 0.86 to 0.96. Synonymous variants: 318 observed, 311.38 expected, observed/expected ratio (o/e) 1.02, 90% interval 0.93 to 1.12.
Homologues: Orthologues: chimpanzee ZNF280D (99% identical), macaque ZNF280D (97% identical), dog ZNF280D (91% identical), pig ZNF280D (88% identical), rabbit ZNF280D (85% identical), guinea pig ZNF280D (78% identical), rat Zfp280d (75% identical), mouse Zfp280d (63% identical). Paralogues in human: ZNF280C (50% identical), ZNF280B (30% identical), ZNF280A (26% identical), ZBTB49 (10% identical), ZBTB21 (9% identical), FEZF2 (8% identical), FEZF1 (8% identical), PRDM13 (7% identical), GFI1 (7% identical), ZBTB14 (7% identical), ZBTB7B (7% identical), BCL6 (7% identical), and 16 more.
Diseases named in the same sentence as ZNF280D in open-access papers:
ZNF280D is named in the same sentence as 4 diseases in open-access papers, as found by Europe PMC text mining. Sharing a sentence is not in itself a finding about the gene and the disease. The quoted sentences say what the papers report.
dyslexia (1 paper, 2023). A learning disorder characterized by an impairment in processing written words. "In general, ZNF280D is sparsely described and has no disease associations in the literature barring dyslexia." (PMID 37221250, 2023).
heart disease (1 paper, 2023). "The zinc finger protein 280d (Zfp280d in mice and ZNF280D in humans) has not been previously associated with heart disease; we have, therefore, made a confirmatory discovery (manually and automatically)." (PMID 37221250, 2023).
infection (1 paper, 2025). The state of being infected such as from the introduction of a foreign agent such as serum, vaccine, antigenic substance or organism. "Moreover, we identified proviral host factors (MPP8 and ZNF280D) as potential targets to limit infection." (PMID 40739040, 2025).
ZNF280D also shares sentences with these, for which no sentence is quoted: cervical cancer (1 paper).